OLFML2B (olfactomedin like 2B)
Synonyms: DKFZP586L151
Tractability: Antibody: UniProt places it where antibodies can reach, with medium confidence; UniProt predicts a signal peptide or a membrane-spanning region; its Gene Ontology location is reachable by antibodies, with medium confidence.
Gene: Protein-coding gene on chromosome 1 (161,983,192 to 162,023,869, reverse strand). Ensembl gene ENSG00000162745.
Subcellular location: Secreted
Subcellular location (Human Protein Atlas): Cytosol; Predicted to be secreted
Gene Ontology:
Molecular function: extracellular matrix binding; identical protein binding
Biological process: signal transduction
Cellular component: extracellular matrix; extracellular region
Genetic constraint (gnomAD): Loss-of-function variants: 53 observed, 71.18 expected, observed/expected ratio (o/e) 0.74, 90% interval 0.6 to 0.94. The upper end of that interval is the gene's LOEUF score, 0.94, which puts it in group 3 of 6, group 1 being the genes least tolerant of losing a copy. Missense variants: 977 observed, 992.95 expected, observed/expected ratio (o/e) 0.98, 90% interval 0.93 to 1.04. Synonymous variants: 385 observed, 414.42 expected, observed/expected ratio (o/e) 0.93, 90% interval 0.85 to 1.01.
Homologues: Orthologues: chimpanzee OLFML2B (99% identical), macaque OLFML2B (96% identical), guinea pig OLFML2B (83% identical), mouse Olfml2b (83% identical), rabbit OLFML2B (83% identical), rat Olfml2b (83% identical), dog OLFML2B (83% identical), pig OLFML2B (83% identical), tropical clawed frog olfml2b (64% identical), zebrafish olfml2ba (48% identical), zebrafish olfml2bb (46% identical). Paralogues in human: OLFML2A (40% identical), OLFM1 (17% identical), OLFM2 (16% identical), MYOC (16% identical), OLFM3 (16% identical), OLFM4 (15% identical), OLFML3 (13% identical), GLDN (13% identical), OLFML1 (12% identical).
Diseases named in the same sentence as OLFML2B in open-access papers:
OLFML2B is named in the same sentence as 29 diseases in open-access papers, as found by Europe PMC text mining. Sharing a sentence is not in itself a finding about the gene and the disease. The quoted sentences say what the papers report.
gastric cancer (13 papers, 2019 to 2025). A primary or metastatic malignant neoplasm involving the stomach. "The overexpression of OLFML2B in gastric cancer may be used as a novel diagnostic and prognostic target for GC." (PMID 33680913, 2020). "The prognostic ability of OLFML2B was only reported in gastric cancer, so it has great research potential in other cancers." (PMID 34868901, 2021). "The remaining prognostic genes such as OLFML2B, RAI14, SERPINE1, and MPND were also reported to be dysregulated and associated with poor prognosis in gastric cancer." (PMID 32908579, 2020). "OLFML2B expression in protein level was examined using IHC, the results showed that OLFML2B was overexpressed in 9 (69.23%) of 13 patients with gastric carcinoma and downregulated in 4 (30.77%) of 13 patients." (PMID 30866865, 2019). "Patients with high expression of OLFML2B had poorer prognosis in gastric cancer." (PMID 34868901, 2021). "In gastric cancer, OLFML2B could promote the growth of gastric cancer cells, maybe serving an oncogene in the development of gastric cancer." (PMID 33015704, 2020). "OLFML2B (Olfactomedin-Like 2B) is an olfactomedin domain-containing protein and may act as an oncogene in the development of gastric cancer." (PMID 33680913, 2020). "In addition to gastric cancer, OLFML2B serves as a biomarker for diagnosis of HCC." (PMID 35873458, 2022). "For RFS, high expression of OLFML2B, MT1M, and SIDT2 indicated a poor RFS of patients with GC, whereas gastric cancer patients with higher expression of CYP4X1 possessed better RFS from TCGA cohort." (PMID 36092901, 2022). "It was previously reported that OLFML2B was overexpressed in gastric cancer tissues compared to normal gastric tissues and exhibited moderate diagnostic potential (AUC = 0.867, P < 0.0001) and was associated with poor survival of gastric cancer." (PMID 37340445, 2023). "Therefore, further biological experiments in vivo and in vitro are required to confirm the functions of OGN, JAM2, RERG, OLFML2B and ADAMTS1 genes in gastric cancer in the future." (PMID 33015704, 2020).
bladder cancer (5 papers, 2020 to 2023). "OLFML2B overexpression was associated with a worse prognosis in GC, and OLFML2B knockdown lowered the migration and proliferation abilities of bladder cancer cell lines." (PMID 37238607, 2023). "In this study, we found that expression levels of OLFML2B increased with increased stage and grade, suggesting that OLFML2B promotes the progression of bladder cancer and increases the risk of invasion and deterioration of bladder cancer." (PMID 34868901, 2021). "In summary, OLFML2B is a robust risk prognostic marker, and it can help patients with bladder cancer improve individualized treatment." (PMID 34868901, 2021). "OLFML2B may be involved in the crosstalk between bladder cancer cells and tumor-associated macrophages, and is a potential immune therapeutic target." (PMID 34868901, 2021). "The prognosis of patients with high expression of OLFML2B was poor in eleven cancers including bladder cancer, which indicates that OLFML2B mainly plays a role in promoting cancer." (PMID 34868901, 2021). "OLFML2B is a new prognostic marker for the individualized treatment of bladder cancer in the future." (PMID 34868901, 2021). "Then, we used small interference RNA to reduce the expression level of OLFML2B in bladder cancer cell line T24." (PMID 34868901, 2021). "Secondly, more bladder cancer cohorts are needed to prove the possibility of OLFML2B as a marker, and more in-depth mechanism experiments are needed to prove the carcinogenicity of OLFML2B." (PMID 34868901, 2021). "We found that patients with high expression of OLFML2B still had a poor prognosis in two small bladder cancer cohorts." (PMID 34868901, 2021). "Because bladder cancer is an immunologically invasive cancer, we explored the relationship between OLFML2B and immune cell infiltration." (PMID 34868901, 2021). "The OLFML2B gene may contribute to the treatment of bladder cancer in the future based on individual prognostic markers." (PMID 37359008, 2023). "In addition, we found that OLFML2B was upregulated in most cancers except bladder cancer, cervical cancer, myeloma, and ovarian cancer, according to the Oncomine database." (PMID 35873458, 2022). "In the enrichment analysis of OLFML2B co-expression genes, we found that these genes were related to the tumor microenvironment, suggesting that OLFML2B may play an important role in the tumor microenvironment of bladder cancer." (PMID 34868901, 2021). "We speculate that bladder cancer cells may secrete OLFML2B into the extracellular matrix and interact with TAM markers to guide TAM to work for itself." (PMID 34868901, 2021). "Finally, the Wound-healing assay and Colony formation assay results showed that the migration and proliferation ability of bladder cancer cell lines decreased after the knockdown of OLFML2B." (PMID 34868901, 2021). "We found that OLFML2B was hypomethylated in bladder cancer (P = 0.0304)." (PMID 34868901, 2021). "We identified OLFML2B as a robust prognostic marker for bladder cancer in five cohorts." (PMID 34868901, 2021). "The methylation status of OLFML2B in bladder cancer was queried using the web tool UALCAN." (PMID 34868901, 2021). "The results showed that OLFML2B was overexpressed in patients with bladder cancer." (PMID 34868901, 2021). "Our experiments showed that OLFML2B was overexpressed in cancer tissues, and si-OLFML2B could significantly reduce the migration and proliferation of bladder cancer cell lines." (PMID 34868901, 2021). "Furthermore, OLFML2B is bound up with tumorigenesis and prognosis in bladder cancer." (PMID 35873458, 2022). "OLFML2B may be involved in the crosstalk between bladder cancer cells and macrophages." (PMID 34868901, 2021). "The remaining 5 genes have not been found to be associated with the prognosis of bladder cancer (BTBD16, OLFML2B, PRRX1, SPINK4, and SPON2)." (PMID 33204728, 2020).
colorectal cancer (3 papers, 2021 to 2023). A primary or metastatic malignant neoplasm that affects the colon or rectum. "Huang and colleagues suggested that OLFML2B and related genes predict prognosis in colorectal cancer patients by m6A modification." (PMID 37676078, 2023). "We found that the miRNA OLFML2B targeting miRNA, miR-30b, is a well-known oncogene suppressor miRNA in colorectal cancer, which may explain the omics relationship here." (PMID 34567063, 2021).
head and neck squamous cell carcinoma (3 papers, 2020 to 2022). A squamous cell carcinoma that arises from any of the following anatomic sites: lip and oral cavity, nasal cavity, paranasal sinuses, pharynx, larynx, and salivary glands. "According to previous studies, OLFML2B is associated with perineural invasion in HNSCC (head and neck squamous cell carcinoma)." (PMID 35873458, 2022). "OLFML2B is a key factor in the perineural infiltration-related protein network of head and neck squamous cell carcinoma." (PMID 34868901, 2021).
osteosarcoma (2 papers, 2021 to 2022). A usually aggressive malignant bone-forming mesenchymal neoplasm, predominantly affecting adolescents and young adults. "OLFML2B can serve as a potential prognostic biomarker for osteosarcoma." (PMID 35873458, 2022). "PODN was regarded as a potential biomarker for the diagnosis and prognosis of osteosarcoma, ACTA2, COL6A1, FAP, OLFML2B and COL6A3, can be used as potential prognostic indicators for osteosarcoma." (PMID 34273970, 2021). "Furthermore, ACTA2, COL6A1, FAP, OLFML2B and COL6A3, can be used as prognosis biomarkers for osteosarcoma." (PMID 34273970, 2021). "Finally, it was determined that PODN has functional relevance in osteosarcoma and additional genes (ACTA2, COL6A1, FAP, OLFML2B and COL6A3) have prognostic significance for osteosarcoma." (PMID 34273970, 2021).
head and neck cancer (1 paper, 2022). A primary or metastatic malignant neoplasm affecting the head and neck. "Meanwhile, the downregulation of OLFML2B was observed in head and neck cancer and melanoma." (PMID 35873458, 2022).
liver cancer (1 paper, 2022). An epithelial or non-epithelial malignant neoplasm that arises from the liver. "In addition, we verified the expression level of OLFML2B in liver cancer tissues by immunohistochemistry, and the results were consistent with those of the database." (PMID 35873458, 2022). "qPCR and immunohistochemistry were used to identify OLFML2B expression in LIHC cell lines and liver cancer tissues." (PMID 35873458, 2022).
medulloblastoma (1 paper, 2025). A malignant, invasive embryonal neoplasm arising from the cerebellum. "The absence of OLFML2B expression in tumor tissues indicates that its role may be limited in the context of medulloblastoma tumor cell proliferation and survival." (PMID 40104502, 2025).
melanoma (1 paper, 2022). A malignant, usually aggressive tumor composed of atypical, neoplastic melanocytes. "Therefore, there may be an improvement in the therapeutic effect of melanoma by targeting OLFML2B." (PMID 35873458, 2022).
renal tumors (1 paper, 2023). "The role of OLFML2B and SYLT1 in renal tumors remains unclear." (PMID 37676078, 2023).
cancer (12 papers, 2019 to 2025). A tumor composed of atypical neoplastic, often pleomorphic cells that invade other tissues. "We analyzed gene coexpression to research the correlation between OLFML2B expression and immune-associated genes in 33 types of cancer, such as chemokines genes, chemokine receptor genes, immune activation genes, immunosuppressive genes, and MHC genes." (PMID 35873458, 2022). "We evaluated the copy number alteration (CNA) and mutation status of OLFML2B, and the results revealed that the top five cancer types with total mutations were BLCA, CHOL, UCEC, LIHC, LUAD, and BRCA." (PMID 35873458, 2022). "The results of the TME analysis certificate that overexpression of OLFML2B is positively related to stromal scores and immune scores but negatively associated with tumor purity in almost all cancers." (PMID 35873458, 2022). "In the association between the expression of OLFML2B and Tregs, M2 was different in the same types of cancers based on various algorithms, possibly owing to the heterogeneous principles." (PMID 35873458, 2022). "We further found that OLFML2B played a role in infiltrating different types of immune cells, such as macrophages and cancer-associated fibroblasts." (PMID 35873458, 2022). "The upregulation of OLFML2B increases the stromal scores by recruiting cancer-associated fibroblasts and other stromal cells, which have been proven to promote tumorigenesis, tumor angiogenesis, neoplasm metastasis, and drug resistance, especially in ESCA, KIRC, LIHC, STAD, and LGG." (PMID 35873458, 2022). "Furthermore, we discovered that OLFML2B is associated with the infiltration of Tregs in several cancers, especially in ESCA, KIRC, KIRP, LIHC, STAD, and UVM." (PMID 35873458, 2022). "In summary, the results of systematical pan-cancer analysis of OLFML2B may corroborate the association between its expression and cancers from several aspects." (PMID 35873458, 2022). "QUE alone largely downregulated some genes with a role in promoting cancer (e.g., OLFML2B, EMILIN2, and CD36), which is consistent with the anticancer potential of this natural extract." (PMID 37755981, 2023). "Many studies have proved that OLFML2B is an important oncogene involved in the regulation of a variety of cancers." (PMID 37676078, 2023). "The outcomes indicated that the expression level of OLFML2B is positively correlated with the stromal scores in all types of cancers and immune scores in 24 cancers." (PMID 35873458, 2022). "The current study explores the possible correlation between OLFML2B, prognosis, and immune infiltration in pan-cancer." (PMID 35873458, 2022). "Meanwhile, we discerned that the upregulation of OLFML2B was positively correlated to CAFs in 23 cancers." (PMID 35873458, 2022). "The outcomes about chemokine receptor genes indicated that OLFML2B expression was related to these in all types of cancers, except UCS." (PMID 35873458, 2022). "Our outcomes suggested that OLFML2B was significantly upregulated or downregulated in several cancers." (PMID 35873458, 2022). "The results illustrated that OLFML2B was upregulated in 14 cancers and downregulated in two cancers." (PMID 35873458, 2022). "As a result, we perform this research as the first pan-cancer analysis of OLFML2B to investigate its function, such as in prognosis, clinicopathology, pathways, TME, immune infiltration, immune-associated genes, MSI, TMB, and drug sensitivity." (PMID 35873458, 2022). "So, we conjectured that OLFML2B played an essential role in cancer progression and tumor immune microenvironment." (PMID 35873458, 2022). "Due to the significant association between OLFML2B and TME in almost all types of cancer, we researched the correlation between OLFML2B expression and immune infiltration based on the “immunedeconv” package in R software (XCELL and QUANTISEQ algorithms)." (PMID 35873458, 2022).
cancer (continued). "Because both analyses showed that OLFML2B was positively correlated with macrophage content, we input cancer-related macrophage markers into the web tool “CellMarker” and obtained experimentally verified markers: CD14, CD68, CD163, CSF1R, ITGAM, and MRC1." (PMID 34868901, 2021). "Relevant studies have suggested that OLFML2B may affect various cancer and immune-related pathways, such as ECM receptor interaction, focal adhesion, and transendothelial migration of leukocytes." (PMID 38778371, 2024). "No matter which kind of algorithms we chose, there still existed diverse types of cancers, where we could find a significant relation between the expression of OLFML2B and immune infiltration." (PMID 35873458, 2022). "Furthermore, OLFML2B expression was negatively associated with immune scores in TGCT and tumor purity in all types of cancers except UCS." (PMID 35873458, 2022). "CCR4 is bound by CCL22, which is positively coexpressed with OLFML2B in 22 cancers." (PMID 35873458, 2022). "OLFML2B overexpresses in multiple cancers, which illustrates that OLFML2B may promote the development of tumors." (PMID 35873458, 2022). "Consequently, it was necessary to investigate the association between the expression level of OLFML2B and TME based on the ESTIMATE algorithm to calculate the stromal scores, immune scores, and tumor purity for pan-cancer." (PMID 35873458, 2022). "OLFML2B may influence various cancer and immune-related pathways, such as the PI3K-Akt signaling pathway, ECM–receptor interaction, focal adhesion, and leukocyte transendothelial migration." (PMID 35873458, 2022). "However, only a few previous studies have focused on OLFML2B in cancer." (PMID 35873458, 2022). "The RSF model identified key predictive genes including OLFML2B, ACTB, and C1QB, and demonstrated broad applicability across multiple cancer types." (PMID 39925852, 2025). "OLFML2B expression was bound up with TMB in 13 cancers, MSI in 10 cancers, and TME in almost all cancers." (PMID 35873458, 2022). "Thus, OLFML2B may be used as a new target for cancer treatment." (PMID 35873458, 2022). "Unsupervised principal component analysis with the main cancer invasiveness-enriched genes (ASPN, GLT8D2, OLFML2B, CRISPLD2, ADAM12, POSTN, and PRRX1) allowed for the discrimination of subgroups of BMAL1-dependent CRC patients (p = 9.9 × 10−4)." (PMID 34065633, 2021). "The highest up-regulated lncRNA was lnc-MMP10-3 (absolute FC = 1469.95) among ESCC tissues versus paired non-carcinoma tissues and a total of 809 genes (e.g. S100A16, OLFML2B, and CAST) were related to lnc-MMP10-3 as the standard of absolute PCCs value > 0.8." (PMID 31235759, 2019). "Furthermore, the coexpression analysis between OLFML2B and MHC genes illustrated that the coexpression relationship existed in diverse cancers, except CESC, CHOL, and UCS." (PMID 35873458, 2022). "However, there is no systematic pan-cancer analysis of OLFML2B, especially in tumor immune response, and we do not understand the role of OLFML2B in tumor immune response." (PMID 35873458, 2022). "Negative prognostic genes such as OLFML2B may promote the adhesion of OV cells to certain components in the ECM through their surface receptors and activate the expression of metalloproteinases to degrade the matrix, thereby promoting cancer progression." (PMID 38778371, 2024).